EPHB4 (EPH receptor B4)
Diseases named in the same sentence as EPHB4 in open-access papers (continued):
Sharing a sentence is not in itself a finding about the gene and the disease.
colorectal cancer (continued). "Nevertheless, our results are in clear contrast to recently published results using carcinoma models like breast and colorectal cancer, where overexpression of EphB4 promotes tumor growth by stimulating tumor angiogenesis through increased EphrinB2 reverse signaling." (PMID 29462967, 2018). "EphA2 and EphB4 are known to be upregulated, particularly in the early stages of colorectal cancer." (PMID 28165374, 2017). "Interestingly, earlier studies using Q-PCR to analyze 53 paired normal and colorectal cancer samples showed that EphB4 is more significantly overexpressed in tumor tissue compared to normal tissue than EphA2." (PMID 28165374, 2017). "The HT‐29 colorectal carcinoma cell line, which needs EphrinB2 to survive, contains abundant EphB4 but not EphB1, EphB2, EphB3, or EphA4 proteins, as observed previously." (PMID 31545551, 2019). "We also verified our predictions on a set of genes that play an important role in colorectal cancer (MLH1, PMS2, EPHB4 ) and could confirm more than 73% of them based on evidence in the literature." (PMID 21171995, 2010). "Interestingly, EphB4 but not EphrinB2 has been identified as a predictive biomarker for therapy response in colorectal cancer patients receiving bevacizumab, with an increased EphB4 expression in non-responders." (PMID 29462967, 2018). "Interestingly, in colorectal cancer patients receiving bevacizumab therapy, EphB4 has been identified as a predictive biomarker, with an increased EphB4 expression in non-responders." (PMID 29462967, 2018). "For example, EphB4 has been identified as a predictive biomarker for the therapy response of colorectal cancer patients receiving the vascular endothelial growth factor (VEGF)-targeting antibody bevacizumab, with an increased EphB4 expression in non-responders." (PMID 33153234, 2020).
colon carcinoma (18 papers, 2004 to 2025). "The c-MYC oncoprotein, a known regulator of glucose metabolism and has previously been linked to EPHB4 in colon carcinoma cells." (PMID 31641103, 2019). "Role of EphB4 in regulating c-Myc has previously been described in colon cancer and likely to play role in other cancers with elevated EphB4." (PMID 40044981, 2025). "As an important member of the EPH family, EPHB4 is usually overexpressed in several tumour types, such as ovarian 27, prostate 28, breast, oesophageal 29 and colon cancer." (PMID 34539874, 2021). "In a comparative study we have shown that EphA2 and EphB4 indeed seem promising targets for image-guided surgery for colon cancer, but with EphB4 having more consistent results." (PMID 32751634, 2020). "In contrast, KSR1 or EPHB4 knockdown significantly decreased cell viability in colon cancer cell lines HCT116 and Caco2 compared to the control siRNA." (PMID 33120942, 2020). "The EphB4 expression relates with stage and grade of colon cancer, contrary to EphB2, whose expression is reduced with the tumor progression, and it is firstly abundant on colon progenitor cells." (PMID 32316101, 2020). "In vitro experiments using antibodies on human colon cancer cells confirmed the possibility of EphB4 as target for imaging." (PMID 28165374, 2017). "The higher EphB4 expression in colon cancer compared to normal mucosa was previously also shown at the mRNA level in 62 tissue pairs, with validation at the protein level in only a few samples." (PMID 28165374, 2017). "As regards EphB receptors, EphB4 and EphB2 showed an opposite expression in colon cancer cells." (PMID 32316101, 2020). "Also, analysis of paired normal colon tissue and colon cancer (n = 26) showed that mRNA levels of EphB2, EphB3, EphB4, and EphA4 are significantly lower in the normal tissue than in the adjacent cancer, whereas levels of EphrinB2 and EphB1 are similar." (PMID 31545551, 2019). "Moreover, combination of bevacizumab with inhibitory EphB4 specific monoclonal antibodies targeting the extracellular fibronectin-like domains significantly inhibited growth of HT-29 colon carcinoma xenografts more than monotherapy." (PMID 29462967, 2018). "The incubation of these colon cancer cells with labeled antibodies against EphB4 demonstrates the principle that targeting of this receptor could be clinically relevant, but this should be further elucidated in pre-clinical studies using relevant mouse models." (PMID 28165374, 2017). "H200 pAb was added to confluent monolayers of the EphB4 positive colon cancer cell line SW480." (PMID 25831049, 2015). "We hypothesized that EphB2 is expressed in normal bladder and lost in bladder cancer, similar to the observation in colon cancer, while induction of EphB4 in bladder cancer provides survival advantage." (PMID 25148033, 2014). "In contrast, EphB4 is overexpressed in colon cancer cells and provides survival advantage." (PMID 25148033, 2014). "Using FUSION, EPH (erythropoietin-producing hepatocellular carcinoma) receptor B4 (EPHB4) was identified as a KSR1-like, cancer-specific regulator of colon tumor survival and progression." (PMID 33120942, 2020). "Recently, a series of EphB4 antibodies has been evaluated for the use of Positron Emission Tomography (PET) in mice xenografted with human HT-29 colon cancer and MDA-MB-231 breast cells, underscoring the value of EphB4 as a target for tumor imaging." (PMID 28165374, 2017). "This response was strongest for ephrin-B1 +EphB2 and ephrin-B1 + EphB3 with the response from ephrin-B1 and EphB4 only producing minor modifications in cell distribution and compartmentalization in the DLD1 colorectal adenocarcinoma and Co115 colon carcinoma cells lines used in that study." (PMID 20624275, 2010). "Northern blotting was performed to determine the frequency of expression of ephrin-B2 and EphB4 in human nonmalignant cell lines and colon cancer cell lines." (PMID 15083195, 2004).
colon carcinoma (continued). "However, the expression of EphB4 mRNA was lower in the nonmalignant cell lines, with the exception of HUVECs, than in the colon cancer cell lines." (PMID 15083195, 2004).
lung carcinoma (18 papers, 2013 to 2025). "The downstream signaling patterns of wild-type and mutated EPHB4 in lung cancer are also reported using high-throughput kinome signatures." (PMID 26073592, 2015). "Finally, we show that EPHB4 mutations can induce broad changes in the kinome signature of lung cancer cells." (PMID 26073592, 2015). "Mutations of EPHB4 in lung cancers have previously been identified, though their significance remains unknown." (PMID 26073592, 2015). "Mutations in EPHB4 have not been previously linked to cellular behavior, and these data provide the first evidence that EPHB4 mutations in lung cancer may confer growth advantages as well as differences in protein modifications." (PMID 26073592, 2015). "Here, we report novel mutations in the EPHB4 gene that cause putative alterations in protein structure as well as increased proliferation in lung cancer cells, and a bioinformatic analysis of several mutations strengthens their association with lung cancer." (PMID 26073592, 2015). "EphB4 mutations have also recently been reported in lung cancer, although their significance is currently unknown." (PMID 23844053, 2013). "However, the functional and structural effects of EPHB4 mutations and their potential significance in the context of lung cancer remain essentially unknown." (PMID 26073592, 2015). "In the lung, microarray data from previous studies indicated that EphB4 is upregulated with lung cancer progression when comparing normal versus adenocarcinoma samples." (PMID 32733636, 2020). "EPHB4 is significant in vascular development but increased EPHB4 expression is found in breast and lung cancers." (PMID 32664863, 2020). "EphB4 plays a key role in numerous kinds of tumor, including lung cancer, esophageal cancer, pancreatic cancer, and gliomas." (PMID 27827952, 2016). "EPHB4 is overexpressed and amplified in several lung cancer subtypes and is necessary for the growth of lung adenocarcinoma xenografts in mice." (PMID 26073592, 2015). "Though this oncogenic role for EPHB4 in lung cancer has been established, its exact function and signaling partners have not been fully investigated." (PMID 26073592, 2015). "Taken together, these data illuminate the role of EPHB4 in lung cancer and further identify EPHB4 as a potentially important therapeutic target." (PMID 26073592, 2015). "Further studies into the nature of these relationships are warranted to elucidate the full scope of EPHB4 biology in lung cancer cells." (PMID 26073592, 2015). "A surprising finding was that EphB4 expression in lung cancer positively correlated with patient survival." (PMID 23844053, 2013). "The suppression of EphB4 in cultured cells was shown via three methods to reduce cell growth, suggesting that EphB4 is a critical cellular survival factor in lung cancer." (PMID 23844053, 2013). "Taken together, these data identify EphB4 as a potentially important driver in the pathogenesis of lung cancer." (PMID 23844053, 2013). "The data reported here demonstrate that EphB4 is significantly overexpressed in lung cancer and its gene locus frequently demonstrates increased copy numbers in lung cancer." (PMID 23844053, 2013). "Here, we demonstrate that EphB4 is overexpressed 3-fold in lung tumors compared to paired normal tissues and frequently exhibits gene copy number increases in lung cancer." (PMID 23844053, 2013). "Taken together, these data suggest an important role for EphB4 as a potential novel therapeutic target in lung cancer." (PMID 23844053, 2013). "Here, we show that EphB4 is an important therapeutic target in lung cancer, as it is overexpressed and often demonstrates increased gene copy numbers." (PMID 23844053, 2013). "We indeed found that ephrin-A3 overexpressed in lung cancer cells can inhibit EphA2 and EphA3 activation by ephrins in trans while overexpression of ephrin-B2 can inhibit activation of EphA3 and EphB4." (PMID 24348920, 2013).
lung carcinoma (continued). "In addition, using hepatocellular carcinoma PDXs and lung cancer cases 1 and 2 PDXs, we established a system for simultaneously staining five membrane protein common cancer antigens EphB4, ROBO1, LAT1, CLDN1, GPC3, and HLA class I in six colors." (PMID 40076777, 2025). "With regards to EPHB4, a previous study targeting exon sequencing and RNA sequencing on GGN lung adenocarcinomas suggested that EPHB4 gene mutations observed in patient with GGN was associated with cell proliferation and cellular motility in lung cancer." (PMID 36059824, 2022). "Previous studies have investigated the role of EphB4 in lung cancer and reported that EphB4 is expressed more strongly in tumor tissues compared to paired normal samples, and knockdown or inhibition of EphB4 attenuates the growth of cancer cells in vitro and in vivo." (PMID 32733636, 2020). "The growth of the established tumors in mouse xenograft models can be halted by single-target strategy, and EphB4 may be a potential novel therapeutic target in lung cancer." (PMID 27827952, 2016). "The 17 exons of EPHB4 were sequenced in lung cancer patient tissues and lung cancer cell lines." (PMID 26073592, 2015). "Additionally, we have shown that EphB4 is crucial for the growth of lung cancer cells in vitro and in vivo and that modulation of EphB4 protein expression has significant effects on the motility of lung cancer cells." (PMID 23844053, 2013). "We sought to systematically study the role of EphB4 in lung cancer." (PMID 23844053, 2013). "It is based on these prior findings that EphB4 may also be considered a positive prognostic indicator in lung cancer given the data presented here." (PMID 23844053, 2013). "The association between osimertinib therapy and EphB4 also demonstrates that osimertinib decreased the expression of EphB4 and that the knockdown of EphB4 reduced the sensitivity of osimertinib in lung carcinoma cell lines regardless of the EGFR mutation status." (PMID 34445227, 2021). "EphB4 and HIF-1α play a vital role in lung cancer by promoting tumor growth, angiogenesis, and metastasis." (PMID 40011266, 2025). "Few other studies have previously investigated the role of EphB4 in lung cancer, and none have done so in such a systematic manner." (PMID 23844053, 2013). "Furthermore, no mutations in EPHB4 were identified, and, in contrast to our findings, many of the alterations in EPH receptors co-occurred with other driver mutations in lung cancer." (PMID 26073592, 2015). "Therefore, EphB4 could play an important role in tumor growth in lung cancer, but the association between EphB4 and EGFR mutations or EGFR-TKIs in lung cancer has not been reported thus far, to the best of our knowledge." (PMID 34445227, 2021).
capillary malformation (17 papers, 2020 to 2026). "Case 117 had an NT of 5.6 mm and carried a heterozygous EPHB4 variant (NM_004444.5):c.2512C>T (p.Arg838Trp), inherited from the mother, who displayed multiple small (1–2 cm) capillary malformations." (PMID 41317105, 2025). "In capillary malformation-AVM with Ephrin type-B receptor 4 (Ephb4) or Ras p21 protein activator 1 (Rasa1) mutation, Col IV accumulates in the EC endoplasmic reticulum, leading to EC apoptotic death." (PMID 38201296, 2024). "RASA1 and EPHB4 germ line mutations are generally associated with capillary malformation-arteriovenous malformation syndrome, a disorder that increases the risk of fast-flow malformations and pleural effusion as well as other lymphatic anomalies." (PMID 39687400, 2024). "Not only germline but also postzygotic mutations in the RASA1 or EPHB4 genes can lead to capillary malformation‐arteriovenous malformation (CM‐AVM) syndrome." (PMID 39498435, 2024). "Patients with reported mutations in either RASA1 or EPHB4 had family histories of capillary malformation." (PMID 39687400, 2024). "These entities are often sporadic but are found in association with variants of the RASA1 and EPHB4 genes (capillary malformation–arteriovenous malformation, CMAVM; OMIM #608354) or ACVRL1, ENG, and SMAD4 genes (hereditary hemorrhagic telangiectasia, HHT; OMIM #187300)." (PMID 40259928, 2025). "RasGAP and EphB4 are clinically important in vascular disorders where mutations in RASA1 and EPHB4 are causal for the most common neonatal neurovascular disorder, vein-of-Galen malformations, and one of the major neurovascular disorders, capillary malformation-arteriovenous malformation syndrome." (PMID 37507023, 2023). "Capillary malformation-arteriovenous malformations (CM-AVMs) caused by a RASA-1 or EPHB4 mutation are characterized as hereditary sporadic or multifocal capillary malformations (CMs), associated with potential fast-flow vascular anomalies underlying erythema lesions." (PMID 32635943, 2020). "A total of 37 studies published between 2003 and 2025 were included, encompassing 148 patients diagnosed with capillary malformation–arteriovenous malformation syndrome (CM-AVM) and genetically confirmed to carry either RASA1 or EPHB4 mutations." (PMID 41398316, 2025). "Another well-described syndrome is capillary malformation–arteriovenous malformation (CM-AVM), caused by mutations in RASA1 (RAS p21 protein activator 1) and EPHB4 (Ephrin type-B receptor 4), characterized by multifocal fast-flow lesions and cutaneous vascular malformations." (PMID 41463317, 2025). "Capillary malformation‐arteriovenous malformation (CM‐AVM) syndrome, with or without Parkes Weber syndrome, is a rare autosomal dominant disease caused by pathogenic RASA1 or EPHB4 variants." (PMID 39498435, 2024). "Capillary malformation-arteriovenous malformation (CM-AVM) is a blood vascular anomaly caused by inherited loss-of-function mutations in RASA1 or EPHB4 genes, which encode p120 Ras GTPase-activating protein (p120 RasGAP/RASA1) and Ephrin receptor B4 (EPHB4)." (PMID 35015735, 2022).
glioma (17 papers, 2012 to 2025). A benign or malignant brain and spinal cord tumor that arises from glial cells (astrocytes, oligodendrocytes, ependymal cells). "It is noteworthy that EphB4 expression increased in human gliomas in a grade-dependent manner and was also associated with the neo-vascularization and with tumor progression and poor prognosis in GBM patients." (PMID 32850441, 2020). "In human glioblastoma multiforme, a large heterogeneity exists in the expression of EphB4 and ephrinB2 depending on the biological characteristics of glioma cells and the associated microenvironment." (PMID 29987450, 2018). "More precisely, high levels of EPHA2 and EPHB4 expression could distinguish high-grade gliomas and NF2-deficient meningiomas." (PMID 38612645, 2024). "Stimulation of glioma cells with their specific ligand, ephrin-B2, induces EphB4 phosphorylation, which suppresses migration, invasion, and Akt signaling." (PMID 41200151, 2025). "The receptor tyrosine kinase EPHB4 is up-regulated in gliomas, and the circRNA ephrin type-B receptor 4 (circEPHB4, hsa_circ_0081519) is produced from this receptor." (PMID 39170516, 2024). "Here we analyzed the expression of ephrinB2 and EphB4 in human glioma, we observed vascular localization of ephrinB2 in physiology and pathology and found a significant survival reduction in patients with elevated ephrinB2 tumor expression." (PMID 35629359, 2022). "Histological detection of ephrinB2 in glioma was very broad; detailed analysis of different tumor compartments shows variable expression of ephrinB2 and EphB4." (PMID 35629359, 2022). "In summary, it appears that the balance of EphB4 and ephrinB2 expression, their respective signaling pathway activation, and special distribution influence glioma growth, development, and invasion essentially." (PMID 35163601, 2022). "Analysis of human glioma specimens, has shown increased mRNA expression levels of EphB4 and ephrinB2 in ECs as well as in xenograft tumor cells." (PMID 35163601, 2022). "Glioma cell implantation and overexpression of endothelial EphB4, reduced the effect of the antiangiogenic therapy significantly." (PMID 35163601, 2022). "Yet, a recent study, examined EphB4 and ephrinB2 expression in glioma in vitro, identified delineated growth suppressive effects of EphB4-signaling following phosphorylation by ephrinB2." (PMID 35163601, 2022). "Apart from vascular resistance mechanisms, endothelial EphB4 overexpression induced a reduction of proapoptotic and antiproliferative effects of sunitinib indicating resistance mechanisms in glioma cells." (PMID 29987450, 2018). "To address these issues, we used one glioma cell line and analyzed the effects of endothelial EphB4 overexpression on vascular resistance using defined hetero- and orthotopic experimental models." (PMID 29987450, 2018). "The clinical significance of EphB4 signaling in human glioma has been emphasized recently identifying the ephrinB2-EphB4 system as a clinically relevant molecular pathway governing progression-free survival and glioma growth in patients." (PMID 29987450, 2018). "Endothelial EphB4 overexpression has been shown to regulate glioma microvascular morphogenesis by aggravating pericyte–endothelial cell interactions." (PMID 29987450, 2018). "Endothelial EphB4 overexpression induces resistance against antiangiogenic therapy in SF126 glioma by altering vascular morphogenesis shifting the microvascular environment towards large, therapy-resistant microvessels." (PMID 29987450, 2018). "It was the aim of the current study to characterize the influence of EphB4 on tumor microcirculation after antiangiogenic treatment using different SF126 glioma models." (PMID 29987450, 2018). "In this regard, EphB4 overexpression reduced glioma growth in orthotopically implanted glioma in our study by leading to reduced proliferation." (PMID 29987450, 2018).